NOTCH1 (notch receptor 1)
Diseases named in the same sentence as NOTCH1 in open-access papers (continued):
Sharing a sentence is not in itself a finding about the gene and the disease.
breast cancer (continued). "Furthermore, in a screen for genes promoting mammary tumour development in BRCA1-deficient mice, Notch1 was identified as a strong driver, and there are several reports indicating that elevated Notch signalling induces and accelerates mammary tumour formation." (PMID 38172915, 2024). "On the one hand, Notch1 has been reported to promote cancer cell migration and invasion and inhibit apoptosis in many tumors, including tongue cancer, pancreatic cancer, and breast cancer, while mechanistic studies in bladder cancer have revealed that Notch1 also serves as an oncogene." (PMID 37760477, 2023). "Autophagy inhibition by Beclin1 silencing inhibits Notch1 degradation, increases breast cancer cell migration and ERβ (known to act as a tumor suppressor in breast cancer), transactivates claudin-6 (CLDN6), and induces CLDN6-related autophagy to suppress migration and invasion in breast cancer." (PMID 36831154, 2023). "Interestingly, in a breast cancer model, BafA1 treatment reduces the growth in cells expressing membrane-tethered, constitutively active NOTCH1 forms, while sparing cells expressing cytoplasmic forms." (PMID 37760535, 2023). "Another study showed that NEDD4L could be directly inhibited by the miR-106b-25, which mediated breast cancer initiation by activating NOTCH1 signaling." (PMID 38027016, 2023). "Likewise, using mouse models, we previously demonstrated that the expression of the endogenous wild-type R-Ras2 protein is quite relevant for Her2- or Notch1-mediated transformation of breast cancer or T cell acute lymphoblastic leukemia, respectively." (PMID 36476833, 2023). "YAP1 expression was positively correlated with Notch1 in breast cancer." (PMID 37759462, 2023). "NOTCH1 regulates cell differentiation, cellular metabolism, cell cycle progression, angiogenesis, self-renewal, and immune function and has been shown to be deregulated in breast cancer." (PMID 36979914, 2023). "Taken together, Notch1 and CD73 expression may associate with poor chemotherapeutic response in breast cancer." (PMID 37391408, 2023). "In addition to hematological diseases, other tumor entities with NOTCH1 activation have been identified, such as breast carcinoma." (PMID 37833915, 2023). "Hypermethylation of the promoters of tumor suppressor genes ATM, NOTCH1, NUP98, PALB2, TSC2, and WRN had all previously been associated with WTC exposure and were again observed to be hypermethylated in WTC EHC compared to NYUWHS breast cancer patients." (PMID 35564499, 2022). "Upregulation may occur in the brain and pancreatic tumors (Notch 1, 2, and 3), breast cancer (Notch 1, 2, 3, and 4), and downregulation is typical for colorectal cancer (Notch 1, 2, and 3)." (PMID 36429127, 2022). "A strong correlation between Pin1 overexpression and high levels of activated Notch1 has been observed in breast cancer patients, and some studies have suggested that Notch1 may directly induce transcription of Pin1." (PMID 36304997, 2022). "Furthermore, a clinical study found that Notch1 correlated to a poor prognosis in patients with breast cancer." (PMID 36139447, 2022). "In addition, suppression of Notch1 via miR-34a can lead to an increase in breast cancer cell chemosensitivity to paclitaxel with a reduction in CSC proliferation and expression of the stemness marker ALDH1." (PMID 35205716, 2022). "Moreover, miR-34a has been shown to have an anti-tumor activity in breast cancer, which blocks the NOTCH1 pathway by functionally targeting Notch1, thereby regulating cell proliferation, migration, and invasion." (PMID 35123522, 2022). "Besides, AMPK stabilizes Notch1 by impairing the interaction between Notch1 and Itch in a kinase activity-dependent manner to potentiate hypoxia-induced breast cancer stemness and drug resistance." (PMID 35508987, 2022). "For example, BRD4 regulates breast cancer dissemination through Jagged1/Notch1 signaling." (PMID 34605158, 2022).
breast cancer (continued). "Moreover, NOTCH1 has a role in oncogenesis and metastasis in a wide range of solid tumors, including breast cancer and NSCLC." (PMID 35565454, 2022). "However, in our earlier work, which focused on the closely related protein Notch4, immuno-staining for Notch1 protein in Breast cancer cell lines-SUM149, Hs578T and HCC1806, showed that NIC1 was excluded from the nucleolus." (PMID 36211456, 2022). "In line with this, in breast cancer, Notch1 and miR-34 expressions were inversely correlated, and miR-34 mimic sensitized chemoresistant breast cancer cells to doxorubicin and paclitaxel, thus suggesting a possible advantage of Notch inhibition by replacing miR-34 in combined therapeutic strategies." (PMID 34680255, 2021). "In Chinese population, while the association of NOTCH2-rs11249433 and NOTCH3-rs1043994 was lacking with breast cancer risk, NOTCH1-rs3124591 was significantly associated with invasive ductal carcinoma and ductal carcinoma in situ." (PMID 34257585, 2021). "Furthermore, this phosphorylation enhances the tumorigenic behavior of both breast and prostate cancer cells, as also suggested by the observed coexpression of PIM1 and NOTCH1 mRNAs in patients with breast cancer." (PMID 33775697, 2021). "Moreover, an anti-Notch1 monoclonal antibody increased the sensitivity of breast cancer cells to doxorubicin through depleting the population of CSC." (PMID 34680255, 2021). "Interestingly, NOTCH1 signaling upregulates Pin1 expression, thereby generating a positive feedback loop for malignant progression in human breast cancers." (PMID 33807199, 2021). "Notch1 is a poor prognostic factor responsible for CSC maintenance in breast cancer." (PMID 34680255, 2021). "Importantly, one downstream effector of Notch1 is the nuclear factor-kB (kB), which normally promotes breast cancer tumorigenesis and progression." (PMID 33976116, 2021). "Thus, inhibition of Notch1 expression can lead to growth suppression and programmed cell death in breast cancer cells." (PMID 33923053, 2021). "Indeed, Notch1 inhibition through miR-34a upregulation contributed to sensitization to paclitaxel in a breast cancer model affecting the pool of CSC." (PMID 34680255, 2021). "Increased expression of EZH2 transforms normal breast epithelial cells, is a marker of aggressive breast cancer, and associates with poor prognosis and EZH2 has been shown to expand stem cell populations in breast cancer though activation of the NOTCH1 pathway." (PMID 33750924, 2021). "BRCA1 has been shown to upregulate Jagged-1 and Notch 1 expression in breast cancers." (PMID 33924995, 2021). "Furthermore, the circRNA_0084043/miR-153-3p/Snail axis promotes malignant melanoma progression and the circRNA-000911/miR-449a/Notch1 axis promotes chemotherapy resistance in breast cancer." (PMID 33504681, 2021). "Activation of the Notch receptor NOTCH1 could induce breast cancer metastasis by upregulating the EMT process, which is mediated by the pro-tumorigenic factor, CYR61." (PMID 34374886, 2021). "To demonstrate whether ADAM10 affects TNBC functions by regulating the Notch1 signaling, we first detected the expression level of Notch1 in different breast cancer cell lines using the western blot and qRT-PCR assays." (PMID 33413403, 2021). "For examples, SNPs in NOTCH1 and NOTCH2 are associated with risk of breast carcinoma." (PMID 34257585, 2021). "Interestingly, a recent study reported that BRD4 modulates the spread of breast cancer by Notch1/Jagged1 signaling." (PMID 33135348, 2020). "Besides this, our group recently described that DYRK2 induces cell apoptosis in a NOTCH1-IC-dependent way using breast cancer cell lines." (PMID 32462403, 2020). "Notch1 and Notch4 have been validated to regulate breast cancer stem cells by recent studies." (PMID 32636747, 2020).
breast cancer (continued). "Using the cancer genome atlas (TCGA) breast cancer cohort (n = 956), a subset of patients with multiple hotspot mutations in the HD or PEST domain of Notch 1, 2 or 3, similar to that observed in T-ALL, were identified, rendering it constitutively active and/or resistant to degradation." (PMID 32575680, 2020). "We show that both Notch-1 and Notch-2 are upregulated in cancer samples compared to healthy tissue, thus emphasizing the important role and dysregulation of the Notch pathway in breast cancer." (PMID 32245259, 2020). "Moreover, ATR–CHK1 activation by ICN1 was also detected in T47D cells, as well as in MCF10A cells treated with the NOTCH1 ligand Jagged1, suggesting a general feature of NOTCH1 to regulate the cell cycle in breast cancer cells." (PMID 32591500, 2020). "We recently published an article which showed Notch1 could also transcriptionally activate MCAM in breast cancer cells." (PMID 32636747, 2020). "In addition, the delivery of miRNA-34a inhibited breast cancer cell migration via targeting Notch-1 signaling." (PMID 32792960, 2020). "In addition, Karsan and colleagues showed that Slug is a direct target gene of Notch1 in breast cancer." (PMID 32391382, 2020). "Moreover, the elevated expression of Notch1 in TECs is correlated with poor prognosis for melanoma, lung adenocarcinoma, and breast carcinoma, as Notch1 activity facilitates metastasis." (PMID 32283668, 2020). "The role of Notch2 in breast cancer is less well characterized with respect to Notch1." (PMID 31379945, 2019). "The results suggest that Nrf2 is a potential molecular target for the treatment of breast cancer and targeting Notch1 signalling pathway may provide a promising strategy for the treatment of Nrf2‐driven breast cancer metastasis." (PMID 30809937, 2019). "Notch1 was found to be over-expressed and hyper-activated in TNBC patients, and high Notch1 levels were associated with reduced overall survival in TNBC/basal breast cancer patients." (PMID 31105691, 2019). "The purpose of this up-to-date review is to provide a detailed overview of the specific role of all four Notch receptors (Notch1, Notch2, Notch3, and Notch4) in TNBCs, thus identifying the Notch signaling pathway deregulation/activation as a pathognomonic feature of this breast cancer subtype." (PMID 31379945, 2019). "For instance, paeoniflorin could induce suppression of invasion in breast cancer cells via inhibition of Notch-1 signaling." (PMID 30886866, 2019). "Mutations were found in NOTCH1–3 at the C-terminal PEST domain, and also in the prolyl-isomerase PIN1 (peptidylprolyl cis/trans isomarase, NIMA-interacting 1), supporting the theory of the involvement of Notch in breast cancer." (PMID 31443481, 2019). "E2 can induce Jag1 and Notch1 expression in breast cancer MCF7 cells; increased Jag1 is abrogated by ER antagonist treatment, suggesting an ER-dependent mechanism corroborated by the discovery of imperfect oestrogen-responsive elements in the 5′ region of Notch1 and Jagged1 genes." (PMID 31868216, 2019). "Although the location of ERα protein expression was different in prostate cancer and breast cancer, tamoxifen could inhibit the expression of NOTCH1 in PCa, in this study." (PMID 31122254, 2019). "It is suggested that Nrf2 is positively correlated with Notch1 in breast cancer." (PMID 30809937, 2019). "The association between np9 gene and several signaling pathways, including WNT, ERK, Akt and Notch1 suggested that probably the over-expression of this gene could play a crucial role in the progression of breast cancer." (PMID 31798679, 2019). "In addition, a correlation has been found between the expression of Notch1 protein and known prognostic factors in breast cancer, analyzed by IHC assay in 115 breast cancer tissues." (PMID 31379945, 2019). "Therefore, we suggest that Nrf2 controls cell proliferation in breast cancer through influencing Notch1 and affecting HES‐1." (PMID 30809937, 2019).
breast cancer (continued). "This may be linked to Notch signaling as Sox2 is activated by Notch1 ICD in TNBC, and Notch signaling mediates paclitaxel and tamoxifen resistance in colon and breast cancer cells." (PMID 30388742, 2018). "Furthermore, Notch-1 has already been validated as a miR-34a-5p target gene in several tumor histotypes such as choriocarcinoma, breast cancer, and hepatocellular carcinoma." (PMID 29857516, 2018). "Similarly, in MCF-7 breast cancer cells, Notch1 canonical signaling upregulated the expression of ABCC1 protein." (PMID 30004402, 2018). "Luminal breast cancers with Notch1 remain hormone responsive." (PMID 30515368, 2018). "One previous study found that S100A16 could promote EMT in breast cancer cells by elevating the expression of transcription factors Notch1, ZEB1, and ZEB2." (PMID 29746588, 2018). "Psoralidin, for example, a natural phenolic compound found in the seeds of Psoralea corylifolia, has been seen to inhibit NOTCH1 in breast cancer stem cells and in breast cancer cells, leading to a growth arrest and inhibition of epithelial to mesenchymal transition (EMT)." (PMID 30057626, 2018). "Among breast cancer subtypes, Notch1 and CD133 were most highly expressed in basal-like tumors." (PMID 30559934, 2018). "Notch1 directly upregulates c-Myc expression in leukemia, lymphoma, and breast cancer cells." (PMID 29423060, 2018). "Furthermore, circulating tumor cells “primed” for breast cancer brain metastases have a specific gene signature (HER2+/EGFR+/HPSE+/Notch1+)." (PMID 30515368, 2018). "Primary breast cancer and glioblastoma cells robustly upregulated HIF2α mRNA expression upon Notch activation in normoxia, using Jagged1 ligand stimulation or expression of Notch1 and 2 ICD." (PMID 29993038, 2018). "Yet, the authors showed that in the breast cancer cell line HHCC1599, harboring a gene rearrangement of Notch1 causing ligand-independent, but γ-secretase dependent activation of Notch, BafA1 had a smaller effect than DAPT in reducing the steady-state levels of NICD and Hes1." (PMID 29996493, 2018). "NOTCH1 is the best studied Notch receptor with regard to breast cancer." (PMID 27888801, 2017). "Additionally, miR-34a can inhibit the proliferation of breast cancer stem cells by down-regulating the NOTCH1 pathway, and miR-34a increases the sensitivity of breast cancer cells to PTX." (PMID 29290947, 2017). "Notch1 signaling might promote breast cancer cell invasion due to the activation of NF-κB and its downstream target genes including MMP-2, MMP-9 and VEGF." (PMID 29104587, 2017). "It was found that visfatin-Notch1 axis contributes to breast cancer progression." (PMID 28724427, 2017). "Moreover, IL-6 promotes breast cancer bone metastasis through Notch-1, and induces mammosphere formation in breast cancer cells through Notch-3." (PMID 28270211, 2017). "The overexpression of ESR1 and NOTCH1 is correlated with breast cancer progression and prognosis." (PMID 28793339, 2017). "In addition, several proteins were identified by KM plotter as potential drug targets, such as S100P, carbonic anhydrase IX (CAIX), Notch1 in breast cancer, aldehyde dehydrogenase 1 (ALDH1) in NSCLC, Notch2 in ovarian cancer." (PMID 28061457, 2017). "Apoptosis in breast cancer cells can occur with abrogation of aberrant Notch1 signaling." (PMID 28724427, 2017). "By targeting NOTCH1, miR-34a can regulate the chemosensitivity of breast cancer to DOX." (PMID 29290947, 2017). "Notch1 might downregulate Slug to maintain the epithelial phenotype and inhibit the migration and invasion of breast cancer cells." (PMID 29104587, 2017). "This may indicate that Notch1 is a key player in epithelial-to-mesenchymal transition (EMT) in breast cancer." (PMID 29104587, 2017).
breast cancer (continued). "Rustighi and coworkers found that activities of Notch1/4 are essential for maintaining the ‘stemness’ character of both normal stem cells and breast cancer stem cells (BCSCs), and that Notch1/4 activity is strongly correlated with self-renewal and chemo resistance of BCSCs." (PMID 29069872, 2017). "Consequently, N9 inhibits proliferation of Notch1-expressing breast cancer cell lines and downregulates expression of Notch target genes." (PMID 28931897, 2017). "Crosstalk between CCR7 and Notch1 promotes stemness in mammary cancer cells and may ultimately potentiate mammary tumor progression." (PMID 28137279, 2017). "Indeed, comparisons between the genes regulated in the epithelial model and those regulated by Notch1 in a breast cancer cell line revealed a surprising extent of overlap." (PMID 26657768, 2016). "In fact, all IDC samples expressed high level of NOTCH1 compared to other types of breast cancers." (PMID 28330128, 2016). "In contrast to the low expression of NUMB in BLBC and ER-negative breast cancer patients, Notch1 had a relatively high expression in these breast cancer patients, demonstrating an apparent opposite trend for the expression of NUMB and Notch1 in breast cancers (lower left and middle)." (PMID 27506933, 2016). "To test the hypothesis, we recruited a sensitive real-time PCR based on SYBR Green I to evaluate the expression of NOTCH1 in breast cancer and adjacent breast tissue samples." (PMID 28330128, 2016). "To investigate whether autophagy affects Notch1-induced migration ability of breast cancer cells, we performed migration and invasion assays." (PMID 27806347, 2016). "Based on these data, we hypothesized that 3,6-DHF may down-regulate Notch1 expression via up-regulation of miR-34a in breast cancer cells and result in suppression of EMT." (PMID 27345219, 2016). "Therefore, high-level expression of NOTCH1 in breast cancer can be used as a prognostic marker for detecting IDC." (PMID 28330128, 2016). "Also, in a mouse model, the Notch1 pathway promotes acquired resistance to tamoxifen in serially passaged breast cancer xenografts." (PMID 26716652, 2016). "More recent studies showed that leptin induced expressions of Notch1, 3, 4 in breast cancer cells, and inhibition of leptin signaling, led to decreased protein expression levels of NICD1, NICD4, Notch3, JAG1 and survivin as well as reduced mRNA levels of Notch receptors, ligands and targets." (PMID 27185268, 2016). "Interestingly, one of the critical protein in balancing Tau turnover is Pin1, a direct target of Notch1 in breast cancer cells." (PMID 27364742, 2016). "This meta-analysis suggested a predictive value of Notch1 expression in breast cancer patients." (PMID 26121683, 2015). "Two published studies, discussed in detail below, allowed development of the hypothesis that activity of Notch1 mediates MRP1 induction in some breast cancers." (PMID 26362310, 2015). "Moreover, an increased likelihood of LNM and higher histological grade were correlated with high Notch1 expression in breast cancer (pooled OR = 1.65, 95%CI: 1.09–2.52, p = 0.064 and I2 = 55%; pooled OR = 1.68, 95%CI: 1.28–2.2, p = 0.737 and I2 = 0.0%)." (PMID 26121683, 2015). "In contrast, higher Notch1 activity was observed in basal type breast cancer, suggesting that theNotch1 inhibitor could be more likely to benefit patients with basal-type breast cancer." (PMID 26121683, 2015). "Likewise, our study showed that the EMT process was closely related to Notch1 signaling in breast cancer cells." (PMID 25645291, 2015). "In light of our studies, Notch1 might downregulate Slug to maintain the epithelial phenotype and inhibit the migration and invasion behavior of breast cancer cells." (PMID 25645291, 2015). "It is generally believed that Notch1 can be used as a progressive biomarker for breast cancer." (PMID 26121683, 2015).